PCSK9 (proprotein convertase subtilisin/kexin type 9)
Diseases named in the same sentence as PCSK9 in open-access papers (continued):
Sharing a sentence is not in itself a finding about the gene and the disease.
Hypercholesterolemia (continued). "Two additional mutations of PCSK9 (D374Y and N157 K) were then identified in Norwegian subjects with clinical diagnose of familial hypercholesterolemia, and the same mutation was observed in a Utah pedigree." (PMID 24278757, 2012). "A role for PCSK9 in the regulation of serum cholesterol levels in humans, is demonstrated by the findings that mutations in the PCSK9 gene have been associated both with hypo- and hypercholesterolemia." (PMID 17328821, 2007). "All gain-of-function mutations in PCSK9 leading to hypercholesterolemia in humans are 100% conserved at the amino acid level across all the primates we sampled." (PMID 17971861, 2007). "We present evidence that a common genetic variant in the PCSK9 gene contributes to polygenic hypercholesterolemia in men of European origin." (PMID 16875509, 2006). "However, almost 60% of these UC patients had hypercholesterolemia, which is associated with higher levels of PCSK9." (PMID 40265438, 2025). "Additionally, three proteins—APO B, APO E, and PCSK9—were associated with hypercholesterolemia, showing an ES of 13.8." (PMID 39445733, 2025). "Hypercholesterolemia is associated with high serum PCSK9 levels." (PMID 40265438, 2025). "The detection of specific CHIP mutations may improve the precision of hypercholesterolaemia therapy prescription, particularly for the more costly therapies such as proprotein convertase subtilisin/kexin type 9 (PCSK9) inhibitors." (PMID 40076674, 2025). "Thus, while gain-of-function mutations of PCSK9 increase the degradation of LDL receptors and enhance hypercholesterolemia, mutations in PCSK9 that diminish its function lower the levels of LDL cholesterol and produce a reduced risk of CVD." (PMID 40662044, 2025). "By elucidating the precise mechanisms through which natural compounds modulate PCSK9, more targeted and effective dietary strategies can be developed to complement conventional pharmacotherapy in the treatment of hypercholesterolemia and associated cardiovascular risks." (PMID 40764605, 2025). "PathogenicLDLR variants, especially in the homozygous state, portend a greatly elevated and early-onset CVD risk, necessitating vigilant management and family screening APOB and PCSK9 variants contribute to hypercholesterolemia as well, but their association with clinical CVD appears weaker." (PMID 41398288, 2025). "Predominantly expressed in the liver, intestine, and kidney, PCSK9 was first recognized as a key regulator of lipid metabolism when gain-of-function mutations in its gene were linked to familial hypercholesterolemia and an increased risk of coronary artery disease." (PMID 41226200, 2025). "Furthermore, it has been observed that Dennd5b–/– mice demonstrate resistance to weight gain induced by dietary intake and exhibit reduced susceptibility to PCSK9-induced hypercholesterolemia." (PMID 39649955, 2024). "The functional characterization of PCSK9:c.∗950C > T showed that this variant could also cause hypercholesterolemia by PCSK9 upregulation according to the observed increase in luciferase expression (up to 41%)." (PMID 40225943, 2024). "Rare gain-of-function mutations in human PCSK9 cause familial hypercholesterolemia." (PMID 38887452, 2024).
Hypercholesterolemia (continued). "Subsequently identified as the third pathogenic gene associated with familial hypercholesterolemia, along with low-density lipoprotein receptors (LDLRs) and apolipoprotein B (ApoB) genes, PCSK9 has been extensively studied concerning its interplay with lipid homeostasis." (PMID 39139638, 2024). "The interest in proprotein convertase subtilisin/kexin type 9 (PCSK9) as a lipid-lowering target arose at the beginning of the present century after the identification of several families with familial hypercholesterolemia (FH) who carried gain-of-function mutations in the gene encoding PCSK9." (PMID 38172901, 2024). "PCSK9 is the third locus associated with familial hypercholesterolemia." (PMID 38887452, 2024). "Finally, the ARCHITECT study evaluated PCSK9 inhibitor-associated plaque modification on CCTA features of patients with familial hypercholesterolemia." (PMID 39125547, 2024). "Because of this, PCSK9 reasonably represents a causal factor in familial hypercholesterolemia." (PMID 39769398, 2024). "Furthermore, several studies have established a connection between PCSK9 levels and myocardial infarction patients, as well as high-risk cardiovascular patients, such as those with hypercholesterolemia and/or diabetes." (PMID 37892538, 2023). "Gain-of-function PCSK9 variants have been identified as missense mutations in the coding region, intronic junctions, as well as in the promoter region that increase PCSK9 transcription and are associated with hypercholesterolemia and coronary heart disease (CHD)." (PMID 38020120, 2023). "Also, tumor-secreted proprotein convertase subtilisin/kexin type 9 (PCSK9) has been implicated in the causation of paraneoplastic hypercholesterolemia." (PMID 37791221, 2023). "A gain-of-function (GOF) mutation in the PCSK9 gene (p.(Ser127Arg)) was identified in two large French families with multiple consanguineous hypercholesterolemia/hyper LDL-C, tendinous xanthomas, acute myocardial infarction (MI), and stroke, which most likely had a common ancestor." (PMID 37510094, 2023). "Family-based studies identified specific mutations in APOB and PCSK9 as etiological factors contributing to development of familial hypercholesterolemia by either impeding the binding of LDL particles to the receptors, thus hindering the uptake, or by enhancing the catabolism of LDL receptors." (PMID 38049831, 2023). "Moreover, PCSK9-i has effectively reduced atherogenic risk in patients with familial hypercholesterolemia." (PMID 37898751, 2023). "Hypercholesterolemia was induced in Dennd5b−/− mice by infection with an adeno-associated virus expressing the proprotein convertase subtilisin/kexin type 9 serine protease (PCSK9) gain-of-function mutation (PCSK9D377Y) and feeding a Western diet for 12 weeks." (PMID 36243100, 2022). "As a result, increased PCSK9 concentrations cause hypercholesterolaemia." (PMID 36289901, 2022). "Advances in genetic engineering have the possibility to build such models in tiny pig strains that can develop hypercholesterolemia under circumstances nearly identical to human hypercholesterolemia that might be linked to PCSK9 study." (PMID 36005422, 2022). "Furthermore, gain of function (GOF) mutations in PCSK9 genes are the cause of familial hypercholesterolemia with significantly higher levels of cholesterol in the blood, whereas loss-of-function mutations (LOF) are associated with hypocholesterolemia." (PMID 35323699, 2022). "Only two individuals (2/309) had P/LP variants in multiple genes: one harbouring predisposition to familial hypercholesterolemia (FH) and long QT syndromes (PCSK9, KCNH2) and the other with predisposition to cancer and hypertrophic cardiomyopathy (SDHD, MYBPC3)." (PMID 36335097, 2022).
Hypercholesterolemia (continued). "In addition, recent studies in patients with familial hypercholesterolemia suggest that beneficial effects of PCSK9 inhibitor therapy on sdLDL particles are associated with an improvement in endothelial function and carotid stiffness." (PMID 35456658, 2022). "PCSK9 was also shown to play major roles in targeting other receptors for degradation, thereby regulating various processes, including hypercholesterolemia and associated atherosclerosis, vascular inflammation, viral infections, and immune checkpoint regulation in cancer." (PMID 34606887, 2021). "For example, PCSK9 variants can cause hypercholesterolemia or hypocholesterolemia." (PMID 34440342, 2021). "In our study, APOB and PCSK9 mutations were synonymous, benign, and patients with these variants probably did not have a monogenic disorder of lipid metabolism, but they had a polygenic form of hypercholesterolemia." (PMID 33807407, 2021). "Interestingly, mice injected with nephrotoxic serum and mice with selective podocyte ablation were found to have increased plasma PCSK9 levels in association with increased proteinuria, hypertriglyceridemia and hypercholesterolemia." (PMID 34442464, 2021). "PCSK9 inhibitors are used for high-risk patients (for secondary prevention or severe primary hypercholesterolemia) who have statin intolerance syndrome or who have an insufficient reduction in LDL-C level while taking the maximum tolerated dose of a statin plus ezetimibe." (PMID 33924893, 2021). "Clinical studies have shown that circulating ApoB served as an independent predictor of renal replacement therapy in DKD patients, and PCSK9 can promote hypercholesterolemia, and PCSK9 concentrations were associated with chronic kidney disease stages and lipid-lowering regimens." (PMID 33889589, 2021). "Beyond lowering LDL, PCSK9 inhibitors may also control thrombo-inflammation, a pleiotropic effect that contributes to risk reduction in patients with uncontrolled hypercholesterolemia and coronary artery disease." (PMID 34681838, 2021). "Thus, high expression of PCSK9 is often associated with the incidence of hypercholesterolemia, and inhibition of PCSK9 expression or activity has been suggested as a tool to treat patients with familial hypercholesterolemia." (PMID 34208231, 2021). "PCSK9 has been identified and linked to the phenotype of familial hypercholesterolemia." (PMID 33895138, 2021). "Interestingly, hypercholesterolemia associated with nephrotic syndrome can be ameliorated by inhibiting proprotein convertase subtilisin/kexin type 9 (PCSK9), a posttranscriptional regulator of the LDL receptor." (PMID 32733268, 2020). "The identification of endogenous modulators of PCSK9’s function could lead to the development of novel diagnostic tests or treatment options for patients suffering hypercholesterolemia in combination with other chronic metabolic diseases." (PMID 32587953, 2020). "Single nucleotide polymorphisms (SNPs) in the human PCSK9 gene have been associated with either hypercholesterolemia or hypocholesterolemia, depending on whether they increase (gain-of-function, GOF) or reduce (loss-of-function, LOF) PCSK9 activity." (PMID 33029265, 2020).
Hypercholesterolemia (continued). "Loss-of-function mutations in PCSK9 could protect from developing more severe forms of hypercholesterolemia." (PMID 32846800, 2020). "PCSK9 is an enzyme accepted as a new biomarker for the lipid metabolism, a novel therapeutic target for hypercholesterolemia, because the inhibition of PCSK9 may be one of the options for lowering cardiovascular risk." (PMID 31915710, 2019). "Recently it has been shown that there is significantly increased PCSK9 within the CSF of Alzheimer’s patients carrying the APOEε4 allele, with a yet unknown pathway, further adding support to the notion that hypercholesterolaemia is a major risk factor for AD." (PMID 30333009, 2018). "This was well established in lipid disorders and the PCSK9 gene, with the discoveries that gain-of-function variants cause hypercholesterolemia, but rare homozygous loss-of-function mutations lead to lower cholesterol levels without any apparent health consequences." (PMID 30089087, 2018). "Specially, PCSK9 was associated significantly with hypercholesterolemia or combined hyperlipidemia; apoC3 was significant in hypertriglyceridemia, hypercholesterolemia, and combined hyperlipidemia; and sdLDL-C was highlighted in all current dyslipidemias classification." (PMID 27713142, 2017). "Several gain-of-function mutations in PCSK9 can induce hypercholesterolemia and atherosclerosis." (PMID 28291840, 2017). "Indeed, missense mutations in PCSK9 increased response to statin therapy in unrelated hypocholesterolemic subjects and familial hypercholesterolemia patients." (PMID 26099511, 2015). "While clearly an attractive treatment for patients with familial hypercholesterolemia who have mutations of the PCSK9 gene and are difficult to treat with statins, the potential of these agents lies in treatment of the larger population of dyslipidemic patients." (PMID 26703752, 2015). "Gain-of-function mutations in PCSK9 lead to high levels of low-density lipoproteins in the blood (hypercholesterolemia) because they promote the degradation of LDL receptors, whereas loss-of-function mutations markedly reduce the levels of low-density lipoproteins." (PMID 23580362, 2013). "Hypercholesterolemia is caused by gain-of-function mutations in the PCSK9 gene." (PMID 22111029, 2012). "A pharmacological inhibition of PCSK9 may, thus, help to manage both the hypercholesterolemia and the postprandial triglyceridemia, two important risk factors of cardiovascular disease." (PMID 24278757, 2012). "Later that year, Abifadel and colleagues reported the discovery of 2 mutations in PCSK9 that resulted in familial hypercholesterolemia (FH), a genetic disease characterized by greatly increased levels of LDL-C and early onset of atherosclerosis and cardiovascular events." (PMID 21352602, 2011). "In humans, gain-of-function mutations in PCSK9 cause a form of familial hypercholesterolemia that manifests with dramatically increased serum levels of LDL-C, while loss-of-function mutations in PCSK9 are associated with significantly decreased LDL-C and cardiovascular risk." (PMID 21352602, 2011).
Hypercholesterolemia (continued). "Thus, PCSK9 variants resulting in a 'gain-of-function' predispose carriers to hypercholesterolemia, whereas PCSK9 variants resulting in a 'loss-of-function' associate with hypocholesterolemia." (PMID 18547436, 2008). "Because defects in PCSK9 cause familial hypercholesterolemia (OMIM∶607786), one could speculate that this SNP could affect the donor's cholesterol levels." (PMID 18704161, 2008). "Moreover, our results suggest that PCSK9, implicated in hypercholesterolemia and hypertriglyceridemia, may synergistically mediate platelet hyperactivity, aligning with clinical studies." (PMID 37892538, 2023). "A similar strategy has been used clinically to treat homozygous hypercholesterolemia using Mipomersen and Inclisiran, which are RNase H1-active ASOs that induce the degradation of mRNAs encoding apolipoprotein B and proprotein convertase subtilisin–kexin type 9 (PCSK9), respectively." (PMID 36737429, 2023). "We hypothesized that reduced absorption of dietary lipids in Dennd5b−/− mice would result in peripheral effects on lipid metabolism and atherosclerotic vascular disease but that PCSK9-induced hypercholesterolemia would overcome the protective effect of Dennd5b deficiency." (PMID 36243100, 2022). "The finding that CVD patients have higher plasma PCSK9 levels is in line with previous reports showing PCSK9 to be associated with the Framingham Risk Score or with inflammation in the acute phase and hypercholesterolemia in patients with acute coronary syndrome." (PMID 32565719, 2020). "Taken together, these results suggest a regulation of PCSK9 by high glucose which could contribute, at least partly, towards understanding the cause of hypercholesterolemia in HCC and its accompanied upshots in terms of altered response of HCC cells towards cancer therapy." (PMID 30386595, 2018). "In summary, synthesizing efficacy metrics and safety rankings, all four PCSK9 monoclonal antibodies provide new options for the treatment of hypercholesterolemia." (PMID 41585950, 2026). "Proprotein convertase subtilisin/kexin type 9 (PCSK9) is a key drug target for the treatment of different hypercholesterolemia‐related diseases." (PMID 41311296, 2026). "This network meta‐analysis (NMA) evaluated four novel proprotein convertase subtilisin/kexin type 9 (PCSK9) monoclonal antibodies for hypercholesterolemia management, comparing their lipid‐lowering efficacy and safety." (PMID 41585950, 2026). "The second report was on a woman with heterozygous familial hypercholesterolemia previously treated with inclisiran, a siRNA targeting proprotein convertase subtilisin/kexin type 9 (PCSK9)." (PMID 41358055, 2026). "While statins and PCSK9 inhibitors are effective in managing hypercholesterolemia, their impacts on brain cholesterol and cognitive health require further investigation." (PMID 39996836, 2025). "The targeting of PCSK9 has emerged as a pivotal therapeutic strategy in the management of hypercholesterolemia and cardiovascular disease." (PMID 40354375, 2025).